RNA5SP529 (RNA, 5S ribosomal pseudogene 529)
Gene: Ribosomal RNA gene on chromosome 1 (144,265,217 to 144,265,326, forward strand). Ensembl gene ENSG00000276442.
Homologues: Orthologues: chimpanzee 5S_rRNA (100% identical). Paralogues in human: 5S_rRNA (100% identical), RNA5SP533 (100% identical), RNA5SP536 (71% identical), RNA5SP443 (70% identical), RNA5S1 (68% identical), RNA5S10 (68% identical), RNA5S11 (68% identical), RNA5S12 (68% identical), RNA5S13 (68% identical), RNA5S14 (68% identical), RNA5S15 (68% identical), RNA5S16 (68% identical), and 26 more.